OR2T5 (olfactory receptor family 2 subfamily T member 5)
Description:
Odorant receptor.
Synonyms: OR1-62
Tractability: Small molecule: it belongs to a druggable protein family. Antibody: UniProt places it where antibodies can reach, with medium confidence; UniProt predicts a signal peptide or a membrane-spanning region; its Gene Ontology location is reachable by antibodies, with medium confidence.
Gene: Protein-coding gene on chromosome 1 (248,488,589 to 248,491,113, forward strand). Ensembl gene ENSG00000203661.
Subcellular location: Cell membrane
Pathways (Reactome):
Sensory Perception: Expression and translocation of olfactory receptors
Gene Ontology:
Molecular function: olfactory receptor activity; G protein-coupled receptor activity
Biological process: detection of chemical stimulus involved in sensory perception of smell; G protein-coupled receptor signaling pathway
Cellular component: plasma membrane; membrane
Genetic constraint (gnomAD): Missense variants: 4 observed, 20.99 expected, observed/expected ratio (o/e) 0.19, 90% interval 0.093 to 0.44. Synonymous variants: 1 observed, 9.48 expected, observed/expected ratio (o/e) 0.11, 90% interval 0.036 to 0.5.
Homologues: Orthologues: dog OR2T4D (83% identical), dog OR2T4C (83% identical), dog OR2T4B (81% identical), mouse Or2t29 (79% identical), mouse Or2t46 (77% identical), mouse Or2t48 (77% identical), rat Olr1428 (77% identical), mouse Or2t49 (76% identical), mouse Or2t47 (76% identical), rat Or2t47 (76% identical), dog OR2T4G (75% identical), mouse Or2t43 (75% identical), and 4 more. Paralogues in human: OR2T29 (99% identical), OR2T4 (90% identical), OR2T10 (70% identical), OR2T3 (65% identical), OR2T2 (65% identical), OR2T35 (65% identical), OR2T34 (64% identical), OR2T11 (63% identical), OR2T1 (62% identical), OR2T27 (61% identical), OR2T6 (58% identical), OR2T33 (53% identical), and 80 more.
Diseases named in the same sentence as OR2T5 in open-access papers:
OR2T5 is named in the same sentence as 1 disease in open-access papers, as found by Europe PMC text mining. Sharing a sentence is not in itself a finding about the gene and the disease.
OR2T5 shares sentences with these, for which no sentence is quoted: dengue (1 paper).